NCOA2 (nuclear receptor coactivator 2)
Diseases named in the same sentence as NCOA2 in open-access papers (continued):
Sharing a sentence is not in itself a finding about the gene and the disease.
cancer (37 papers, 2008 to 2025). A tumor composed of atypical neoplastic, often pleomorphic cells that invade other tissues. "Abnormally expressed NCOA2 is usually associated with signal transduction and disease progression and is a potential drug target for many cancers." (PMID 34194527, 2021). "The NCOA2 gene plays a crucial role in the occurrence, development, and metastasis in many malignant tumors by activating the WNT pathway." (PMID 36090994, 2022). "NCOA2-based fusion oncogenes identified in different cancer subtypes." (PMID 40599857, 2025). "NCOA2, KDM1A, KDM4A, KDM5B and MED1 are AR coregulators implicated in prostate and other cancers." (PMID 26461474, 2015). "Previous studies have indicated NCOA2 is regulated by miR137 in other cancer types." (PMID 26461474, 2015). "Thus, the presence of the AD1/CID and AD2 domains of NCOA2 seems to be essential for the transformation capacity of the various cancer fusion genes." (PMID 24839999, 2014). "NCOA2 and its close family member, NCOA1, are common fusion partners in cancer encompassing soft tissue sarcoma, prostate and breast cancer and acute myeloid leukemia as examples." (PMID 40599857, 2025). "Meanwhile, SLC25A13 and its neighboring genes were enriched in transcription factor target genes, including MEF2C, NCOA2, SNAI1, and SOX10 target genes, which were participated in the cancer progression." (PMID 35607442, 2022). "This comparison confirmed significant positive enrichment in cancer for all but 2 AR target gene sets (SMARCA4- and NCOA2-dependent)." (PMID 28826481, 2017). "Although epigenetic loss of miR137 contributes to increased KDM1A expression in colo-rectal and oral cancers respectively, the mechanisms resulting in increased KDM1A and NCOA2 in PCa cells are not well understood." (PMID 26461474, 2015). "Notably, the RXRA protein was in protein complexes with RARA, PPARG, NCOA1, NCOA2, and NCOR2 cancer drivers." (PMID 29572294, 2018). "Cancer cell type specific co-regulators included SP1, NCOA1, NCOA2, and PIAS1." (PMID 28117763, 2017). "Putative cancer drivers with a propensity to carry clonal SCNAs were an android receptor gene, the RNA gene XIST, the BRCA1 binding partners RBBP7 and NCOA2, a BRCC3 metaloprotease unit of the BRISC complex and CSTF2 that prevents inappropriate RNA processing at sites of DNA repair." (PMID 26632267, 2015).
bacterial infection (1 paper, 2020). "This study was also the first to report that NCOA1 and NCOA2 were negatively associated with PCT in the serum (a validation factor predicts bacterial infection)." (PMID 32884936, 2020). "This probably shows that NCOA1 and NCOA2 might be protective factors against bacterial infection." (PMID 32884936, 2020).
hematological cancers (1 paper, 2012). "For example, aberrant formation of fusion proteins through chromosomal translocations of HATs such as E1A-binding protein p300 (EP300), nuclear receptor coactivator-2 (NCOA2), MYST3 [histone acetyltransferase (monocytic leukemia) 3] and MYST4 have been identified in hematological cancers." (PMID 23162793, 2012).
NCOA2 also shares sentences with these, for which no sentence is quoted: acute myeloid leukemia (14 papers); osteosarcoma (4); alveolar rhabdomyosarcoma (3); colon cancer (3); soft tissue tumors (3); spindle cell neoplasm (3); acute leukemia (2); acute promyelocytic leukemia (2); bone tumor (2); cervical carcinoma (2); diffuse large B-cell lymphoma (2); hepatocellular carcinoma (2); lymphoma (2); uterine sarcoma (2); acute lymphoblastic leukemia (1); acute mixed-lineage leukemia (1); astrocytic tumor (1); bladder tumor (1); breast neoplasm (1); cardiac failure (1); childhood leukemia (1); chondroblastoma (1); chronic lymphocytic leukemia (1); CNS tumors (1); Cohen syndrome (1); depression (1); embryonal rhabdomyosarcoma (1); giant cell tumor (1); giant cell tumor of bone (1); glioblastoma (1).
A further 31 diseases each share a sentence with NCOA2 in 1 paper.